BMPR1B (bone morphogenetic protein receptor type 1B)
Diseases named in the same sentence as BMPR1B in open-access papers (continued):
Sharing a sentence is not in itself a finding about the gene and the disease.
tumor (continued). "The size of the tumor also affected the expression of BMP3 (P = 0.0047), BMP7 (P = 0.0210), BMPR1B (P = 0.0460), ACVR2A (P = 0.0350), ACVRL1 (P = 0.0045), TGFBR2 (P = 0.0170), and TGFBR3 (P = 0.0150) according to the K-W test." (PMID 34036102, 2021). "Since previous studies using GBM-TICs have shown tumor-to-tumor variation in the expression of BMP receptors, we first determined the mRNA levels of BMP7, BMPR1A, BMPR1B and BMPR2 genes by real-time qRT-PCR in our primary cell lines." (PMID 25860932, 2015). "Consistent with tumor suppressive role of BMP pathway, we found that up-regulation of BMPR1B gene by disruption of miR-125b binding had protective effect against abnormal cell proliferation, with suppression of CA125 expression and serum release of CA125." (PMID 24339876, 2013). "Integration of all these data unveiled that the BMP-responsive (i.e. High PROGENy TGF-β/BMP score) pool of tumor cells correlates significantly with BMP receptors expression, in particular to BMPR2, BMPR1B, BMPR1A, and ACVR1 levels, respectively in 8, 5, 5, and 4 out of 10 samples." (PMID 39373720, 2024). "BMPR1B expression was upregulated in the HCT 116 PCTK1-KO cells and the xenograft tumor tissues." (PMID 37373155, 2023). "Along with our data, all of these findings suggest that reduced expression of BMPR1B and BMPR2, and/or increased expression of BMPR1A, may play a role in the determination of a proliferative cell fate, at least in some types of tumours." (PMID 32714600, 2020). "Significantly downregulated genes in NHT tumours (DESeq comparison; Benjamini-Hochberg P <0.05) were typically androgen responsive (for example, TMPRSS2, KLK3, BMPR1B, TPD52) or steroidogenesis-related (for example, DHCR24, SCD), consistent with a reduction in androgen receptor activity." (PMID 25155515, 2014). "For MCF-7 cells, BMPR1B overexpression could enhance proliferation (down), migration (down) and clone formation of the MCF7 cells in vitro and could promote tumor formation and growth in vivo." (PMID 37644609, 2023). "However, tumor-bearing experiment showed BMPR1B did not change the non-tumorigenic property of MCF10A cells in vivo." (PMID 37644609, 2023).
cancer (20 papers, 2009 to 2025). A tumor composed of atypical neoplastic, often pleomorphic cells that invade other tissues. "The targeting of BMPR1B by miR-125b and the possibility that genetic variants disrupt this target site and play a role in cancer have been previously studied." (PMID 23091610, 2012). "The somatic mutation in BMPR1B is located in a target site of miR-125b; germline mutations in this target site have previously been both shown to disrupt regulation of BMPR1B by miR-125b and linked with cancer." (PMID 23091610, 2012). "In sum, our results indicate that PCTK1 suppresses cancer progression and improves chemoresponse by downregulating the BMPR1B–Smad1/5/8 signaling pathway in CRC." (PMID 37373155, 2023). "Compared with the normal zone, the highly expressed BMPR1B gene promotes the tumorigenic ability of cancer cells in the interface zone." (PMID 37644609, 2023). "The function of BMPR1B is involved in mammalian ovarian follicle development, animal embryonic development, bone tissue formation, cancer cell growth, and brain tissue recovery." (PMID 32375413, 2020). "Finally, BMPR1B-KD partially reversed cell proliferation, cancer stemness, and chemoresistance in PCTK1-KO cells." (PMID 37373155, 2023). "Specifically, we identify putative miRNA target sites in the 3′UTRs of BMPR1B, KLK3, and SPRY4 that are disrupted by both somatic and germline mutations and, also, are in linkage disequilibrium blocks with high scoring markers from cancer association studies." (PMID 23091610, 2012). "BMPs, cytokines that control the function of many types of cells, exert their role through BMPR1A, BMPR1B, and BMPR2 class receptors with many other receptors in each class, and loss of function can be associated with muscular-skeletal and, cardiovascular diseases, cancer, or CP." (PMID 37238140, 2023). "Taken together, our results indicated that PCTK1 suppresses proliferation and cancer stemness and increases the chemoresponse of CRC through the BMPR1B–Smad1/5/8 signaling pathway." (PMID 37373155, 2023). "BMX, BMPR1B, BTK, and MDC1 belong to the COSMIC_mut gene set, and CSNK2A2 belongs to the COSMIC_other gene set, while ASH2L belongs to the non-cancer gene set." (PMID 19765316, 2009). "BMPR1B's involvement in the bone morphogenetic protein (BMP) signaling pathway suggests a potential role in cellular growth and differentiation, aligning with the observed characteristics of cancer cells." (PMID 38524085, 2024). "KEGG analysis showed that ACVR1, SMAD1, ZFYVE9, BMPR1B, and TGFB3 were related to regulating proteoglycan in cancer, focal adhesion, tight junction, PI3K-Akt signaling pathway, cell adhesion molecules (CAMs), Rap1 signaling pathway, osteoclast differentiation, and Hippo signaling pathway." (PMID 34725559, 2021). "Notably, pathways related to cancer, such as MF: cytokine binding and KEGG: Cell adhesion molecules, suggested that the downregulation of PCTK1 and upregulation of BMPR1B may influence cancer cell proliferation and drug sensitivity through mechanisms associated with cell adhesion molecules." (PMID 37373155, 2023). "In addition, downregulation of the BMP receptors BMPR1A, BMPR1B, and BMPPR2 in COL1-PC3SFRP2 suggests that the secreted BMPs might be not utilized by the cancer cells in an autocrine manner." (PMID 36552843, 2022).
kidney diseases (1 paper, 2022). "Among the predicted mRNAs, S1PR5, STAT3, TBR1, and BMPR1B were found to be related to some kidney diseases, as well." (PMID 36536378, 2022). "Moreover, among the predicted targeted mRNAs, S1PR5, STAT3, TBR1 and BMPR1B were found to be related to some kidney diseases." (PMID 36536378, 2022).
skeletal dysplasia (1 paper, 2024). Any Mendelian diseases that affects growth and development of the skeleton. "The identification of a BMPR1B variant (c.1460T>A p.(Val487Asp)) prompts the clinician to consider potential alternative skeletal dysplasias." (PMID 38879467, 2024).
BMPR1B also shares sentences with these, for which no sentence is quoted: hypergonadotrophic hypogonadism (2 papers); triple-negative breast carcinoma (2); acute myelomonocytic leukemia (1); acute promyelocytic leukemia (1); adenoma (1); anemia (1); Anophthalmia (1); basal cell carcinoma (1); benign ovarian tumors (1); Burkitt lymphoma (1); cardiovascular diseases (1); cleft lip (1); cleidocranial dysplasia (1); colorectal cancer (1); cyst (1); dementia (1); diabetes (1); Fanconi anemia (1); fibrodysplasia ossificans progressiva (1); gastric cancer (1); hematological malignancies (1); hyperostosis (1); Hypertension (1); hypospadias (1); Loeys-Dietz syndrome (1); microphthalmia (1); multiple myeloma (1); Myhre syndrome (1); osteoarthritis (1); polydactyly (1).
A further 1 disease shares a sentence with BMPR1B in 1 paper.